KLF15 (KLF transcription factor 15)
Description:
Transcriptional regulator that binds to the GA element of the CLCNKA promoter. Binds to the KCNIP2 promoter and regulates KCNIP2 circadian expression in the heart (By similarity). Is a repressor of CCN2 expression, involved in the control of cardiac fibrosis. It is also involved in the control of cardiac hypertrophy acting through the inhibition of MEF2A and GATA4 (By similarity). Involved in podocyte differentiation (By similarity). Inhibits MYOCD activity. Inhibits NF-kappa-B activation through repression of EP300-dependent RELA acetylation.
Synonyms: KKLF
Tractability: PROTAC: ubiquitination databases record sites on it.
Gene: Protein-coding gene on chromosome 3 (126,342,635 to 126,357,458, reverse strand). Ensembl gene ENSG00000163884.
Subcellular location: Nucleus
Subcellular location (Human Protein Atlas): Nuclear speckles; Nucleoplasm; Vesicles
Pathways (Reactome):
Circadian clock: BMAL1:CLOCK,NPAS2 activates circadian expression
Gene Ontology:
Molecular function: DNA-binding transcription activator activity, RNA polymerase II-specific; protein binding; RNA polymerase II cis-regulatory region sequence-specific DNA binding; RNA polymerase II transcription regulatory region sequence-specific DNA binding; sequence-specific double-stranded DNA binding; DNA-binding transcription factor activity, RNA polymerase II-specific; transcription cis-regulatory region binding; DNA binding; DNA-binding transcription factor activity
Biological process: negative regulation of peptidyl-lysine acetylation; positive regulation of transcription by RNA polymerase II; podocyte differentiation; regulation of transcription by RNA polymerase II; cardiac muscle hypertrophy in response to stress; cellular response to endothelin; negative regulation of collagen biosynthetic process; negative regulation of transforming growth factor beta production; regulation of gene expression
Cellular component: nuclear speck; nucleoplasm; nucleus; chromatin
Genetic constraint (gnomAD): Loss-of-function variants: 4 observed, 22.17 expected, observed/expected ratio (o/e) 0.18, 90% interval 0.088 to 0.41. The upper end of that interval is the gene's LOEUF score, 0.41, which puts it in group 1 of 6, group 1 being the genes least tolerant of losing a copy. Missense variants: 496 observed, 547.36 expected, observed/expected ratio (o/e) 0.91, 90% interval 0.84 to 0.98. Synonymous variants: 246 observed, 230.6 expected, observed/expected ratio (o/e) 1.07, 90% interval 0.96 to 1.19.
Homologues: Orthologues: chimpanzee KLF15 (99% identical), macaque KLF15 (98% identical), dog KLF15 (88% identical), guinea pig KLF15 (87% identical), rabbit KLF15 (86% identical), pig KLF15 (85% identical), mouse Klf15 (85% identical), rat Klf15 (84% identical), tropical clawed frog klf15 (60% identical), zebrafish klf15 (57% identical). Paralogues in human: KLF4 (24% identical), KLF11 (21% identical), KLF2 (21% identical), KLF5 (21% identical), KLF1 (21% identical), KLF12 (20% identical), KLF8 (20% identical), KLF10 (19% identical), KLF3 (19% identical), KLF7 (19% identical), KLF18 (19% identical), KLF17 (18% identical), and 10 more.
Diseases named in the same sentence as KLF15 in open-access papers:
KLF15 is named in the same sentence as 121 diseases in open-access papers, as found by Europe PMC text mining. Sharing a sentence is not in itself a finding about the gene and the disease. The quoted sentences say what the papers report.
cardiac hypertrophy (27 papers, 2012 to 2025). "They found that the downregulation of circRNA CHRC was associated with cardiac hypertrophy, and it affected the progression of cardiac hypertrophy and HF by interacting with miR‐431‐5p to regulate the key TF Krüppel‐like factor 15 (KLF15)." (PMID 39239069, 2024). "Single nucleotide polymorphisms in KLF15 are strongly related to cardiac hypertrophy, and their deletion or inhibition leads to left ventricular hypertrophy in diabetic patients." (PMID 38516000, 2024). "Myocardial hypertrophy causes cardiac systolic and diastolic dysfunction, and KLF15 is a crucial negative regulator of diabetic cardiomyopathy-induced cardiac dysfunction and myocardial fibrosis." (PMID 38516000, 2024). "Previous works have highlighted KLF15 deficient mice develop severe cardiac hypertrophy and heart failure under pressure overload, KLF15 is a direct and independent regulator of myocardial lipid flux and systemic metabolic homeostasis." (PMID 36810848, 2023). "Overall, regardless of the model used, the results have consistently shown that loss of KLF15 contributes to the development of cardiac hypertrophy." (PMID 29702551, 2018). "In pathological cardiac hypertrophy caused by pressure overload in vivo or by phenylephrine (PE) treatment of NRCMs in vitro, the expressions of KLF15 and BCAA degradation enzymes were decreased, whereas glucose utilization increased." (PMID 30050148, 2018). "Therefore, we propose that loss of Klf15 mediates the development of cardiac hypertrophy and heart failure in Mrps5cKO hearts in response to mitochondrial stress." (PMID 36949106, 2023). "Importantly, single nucleotide polymorphisms in KLF15 have been associated with cardiac hypertrophy in patients with diabetes mellitus, and in experimental chronic kidney disease, ventricular hypertrophy is associated with reduced expression of cardiac KLF15." (PMID 33809104, 2021). "Previous in vivo studies regardless of the experimental model used have consistently shown that the loss or reduction of KLF15 removes the ability to repress key cardiac transcription factors that enable growth contributing to the development of cardiac hypertrophy." (PMID 29970016, 2018). "Using recombinant adeno-associated virusses (rAAV) we have overexpressed KLF15 specifically in the mouse heart and provide the first evidence that elevation of cardiac KLF15 levels prevents the development of cardiac hypertrophy in a model of Angiotensin II induced hypertrophy." (PMID 22586493, 2012). "Accordingly, the combinatorial GR+KLF15 knockdown blocked the treatment effects on diastolic dysfunction (E/e′), stroke volume, cardiac hypertrophy (heart weight/tibia length), and insulin-driven glucose uptake." (PMID 39378111, 2024). "KLF15 represses the transcriptional activity of MRTFs in cardiomyocytes and prevents Ang II-indcued cardiac hypertrophy by interacting with MRTF." (PMID 38582447, 2024). "Since BCAAs promote the hypertrophic growth of cardiomyocytes through the activation of mTOR signaling, the KLF15-mediated activation of BCAA degradation tends to prevent cardiac hypertrophy." (PMID 39795113, 2024). "This beneficial action of KLF15 on cardiac hypertrophy is the result of suppressing the accumulation of BCAAs and BCKAs." (PMID 39795113, 2024). "On the other hand, KLF15 is abundantly expressed in the cardiovascular system and is a negative regulator of cardiac hypertrophy, ensuring appropriate cardiac responses to physiological stress signals." (PMID 38516000, 2024). "In mice, loss of KLF15 results in reduced BCAA catabolism and concomitant cardiac hypertrophy, including increased heart weight and exaggerated expression of hypertrophic genes." (PMID 37302544, 2023). "Encouraged by the findings that overexpression of Klf15 in neonatal Mrps5cKO mice was sufficient to prevent the development of cardiac hypertrophy, we explored the potential for Klf15 in the treatment of cardiac defects in adult Mrps5 mutant mice." (PMID 36949106, 2023).
cardiac hypertrophy (continued). "In the early stages during which mitochondrial function is retained, the primary role of Klf15 is to inhibit cardiac hypertrophy by regulating hypertrophic gene expression." (PMID 36949106, 2023). "Similar to what we reported previously, AAV9-mediated overexpression of Klf15 preserved cardiac function and repressed cardiac hypertrophy." (PMID 36949106, 2023). "KLF15 is an inhibitor of cardiac hypertrophy in which overexpression in neonatal rat ventricular cardiomyocytes inhibits cell size, protein synthesis, and hypertrophy-related gene expression." (PMID 35741813, 2022). "Experimental evidence suggested that KLF15 functions as a transcription repressor of cardiac hypertrophy and fibrosis." (PMID 33869197, 2021). "A previous study showed that KLF15 suppressed isoproterenol-induced cardiac hypertrophy and fibrosis by inhibiting mTOR signaling." (PMID 33869197, 2021). "Compared to the wild-type mice, KLF15 knockout (KO) mice aggravated Ang II-induced cardiac hypertrophy and fibrosis." (PMID 33869197, 2021). "KLF15 modulates the transcription of several target genes that are involved in various physiological processes, such as fibrosis, cardiac hypertrophy, obesity, inflammation, insulin resistance, and diabetes." (PMID 30842568, 2019). "CTGF, a key mediator of fibrosis in pathological cardiac hypertrophy, is negatively regulated by KLF15 and increased TGFβ levels activate p38-MAPK signaling which downregulates KLF15 leading myocardin to bind to SRF and to activation of cardiotrophic genes." (PMID 29702551, 2018). "This review provides a summary of experimental and human studies that have investigated the role of KLF15 in the development of cardiac hypertrophy." (PMID 29702551, 2018). "Both in vitro and in vivo studies support a role for KLF15 as a repressor of pathological cardiac hypertrophy and fibrosis." (PMID 29702551, 2018). "In the past decade, there has been increasing evidence from both experimental and human studies that KLF15 is an important regulator of cardiac hypertrophy." (PMID 29702551, 2018). "KLF15 null mice are viable but develop cardiac hypertrophy and heart failure in response to TAC and angiotensin II (Ang II) infusion." (PMID 29970016, 2018). "This review provides a summary of the experimental and human studies that have investigated the role of KLF15 in the development of cardiac hypertrophy." (PMID 29702551, 2018). "KLF15 represses cardiac hypertrophy in part through the modulation of the activity of GATA4 and MEF2, which are central mediators of hypertrophic remodelling acting through ANP and BNP." (PMID 29970016, 2018). "There is now compelling evidence that the transcription factor Kruppel-like factor 15 (KLF15) is an important negative regulator of cardiac hypertrophy in both experimental models and in man." (PMID 29702551, 2018). "In mice, adenoviral overexpression of KLF15 in the heart prevents the development of Ang II induced cardiac hypertrophy." (PMID 29970016, 2018). "The therapeutic potential of KLF15 overexpression on LVH in mice was examined using recombinant adenovirus (AAV9) to overexpress KLF15 and Ang II infusion to stimulate cardiac hypertrophy." (PMID 29702551, 2018). "The studies clearly support a pathological role of KLF15 in the development of cardiac hypertrophy and identify KLF15 as part of a transcriptional pathway regulating the cardiac response to hypertrophic stimuli." (PMID 29702551, 2018). "One possibility is that genetic variation disrupts the ability of KLF15 to repress hypertrophic transcriptional factors, leading to increased expression of these genes and thus cardiac hypertrophy." (PMID 28400202, 2017). "KLF15 null mice develop cardiac hypertrophy and heart failure in response to pressure overload, whilst overexpression of KLF15 reduces cell size and prevents the development of angiotensin II induced hypertrophy." (PMID 28400202, 2017).
cardiac hypertrophy (continued). "The transcriptional factor Kruppel like factor 15 (KLF15) is expressed in the heart and acts as a repressor of cardiac hypertrophy in experimental models." (PMID 28400202, 2017). "Third, we investigated if overexpression of KLF15 in the heart has therapeutic potential for the repression of cardiac hypertrophy." (PMID 22586493, 2012). "Previous studies have shown that KLF15 inhibits cardiac hypertrophy by repressing the activity of pivotal cardiac transcription factors such as GATA4, MEF2 and myocardin." (PMID 22586493, 2012). "KLF15 is an endogenous repressor of cardiac hypertrophy, as was evidenced by the fact that KLF15 null mice have exaggerated cardiac hypertrophy and develop heart failure." (PMID 22586493, 2012). "Similar to these functional observations, we confirmed exacerbated reduced LV function in response to TAC along with cardiac hypertrophy and fibrosis as well as accentuated LV dilation after AngII infusion in Klf15 KO mice." (PMID 22767436, 2012). "During cardiac hypertrophy and heart failure, KLF15 is consistently downregulated in patients, mice and rat models." (PMID 22586493, 2012). "In addition, KLF15 is an important negative regulator of cardiac hypertrophy, which has been confirmed to be decreased in patients with hypertensive nephropathy." (PMID 39135690, 2024). "In addition to its function in regulating cardiac hypertrophy, previous research also demonstrated that Klf15 plays an important role in the regulation of gluconeogenesis." (PMID 36949106, 2023). "Moreover, mRNA levels of ANP and BNP were higher in KLF15 KO mice compared with the WT mice, which indicated deteriorated cardiac hypertrophy." (PMID 33869197, 2021). "Next, we tested whether overexpression of KLF15 or KLF15-ΔTAD can reverse Ang II-induced cardiac hypertrophy and fibrosis." (PMID 33869197, 2021). "In this study, we sought to determine whether KLF15 negatively regulates chemokine-mediated macrophage recruitment, which exacerbates cardiac hypertrophy and fibrosis in Ang II-induced hypertension." (PMID 33869197, 2021). "Importantly, in the Klf15-null mice, cardiac pathologies are observed, such as cardiac hypertrophy and fibrosis, which suggest that KLF15 controls protein synthesis and proteolysis, likely through the regulation of the BCAA homeostasis." (PMID 31973180, 2020). "Overexpression of Klf15 in murine heart has been shown to inhibit cardiac hypertrophy." (PMID 31553739, 2019). "Of these only KLF4, KLF5, KLF10, KLF11 and KLF15 have been studied in cardiac hypertrophy." (PMID 29970016, 2018). "A number of mechanisms by which KLF15 contributes to cardiac hypertrophy have been proposed." (PMID 29702551, 2018). "The current study focussed on the change in expression of KLF15, and future studies that examine the concomitant expression of several KLFs in cardiac hypertrophy may be informative." (PMID 29970016, 2018). "In addition to repressing cardiac hypertrophy, KLF15 is a transcriptional inhibitor of cardiac fibrosis." (PMID 28400202, 2017). "Using recombinant adeno-associated viruses (rAAV) we have overexpressed KLF15 specifically in the mouse heart and provide the first evidence that elevation of cardiac KLF15 levels prevents the development of cardiac hypertrophy in a model of Angiotensin II induced hypertrophy." (PMID 22586493, 2012). "Overall, these studies indicate that overexpression of KLF15 in the heart may provide a novel therapeutic target to counteract cardiac hypertrophy and overt heart failure." (PMID 22586493, 2012). "We investigated whether overexpression of KLF15 in the mouse heart is sufficient to prevent the development of cardiac hypertrophy and fibrosis in response to AngII-induced hypertension." (PMID 22586493, 2012). "Future studies are warranted to establish whether overexpression of KLF15 improves cardiac function and whether it can also prevent hypertrophy in more severe models of hypertrophy and heart failure, such as transverse aortic constriction." (PMID 22586493, 2012).
cardiac hypertrophy (continued). "It has been shown that KLF15 is an important negative regulator of cardiac hypertrophy, and loss or repression of KLF15 leads to left ventricle hypertrophy, due to lack of inhibition of pro-hypertrophic transcription factors and stimulation of trophic and fibrotic signaling pathways." (PMID 33809104, 2021). "To determine whether overexpression of KLF15 represses pressure overload-induced cardiac hypertrophy, we induced hypertrophy a week after injecting mice with the rAAV9-KLF15 and rAAV9–GFP virus, through continuous infusion of AngII (1.5 μg/g/day) via subcutaneously placed osmotic minipumps." (PMID 22586493, 2012). "MRPS5 deficiency disrupts mitochondrial ultrastructure, impairs ATP production, and suppresses the expression of Krüppel-like factor 15 (KLF15) via the c-Myc-mediated signaling pathway, leading to metabolic dysregulation, myocardial hypertrophy, and HF." (PMID 40734976, 2025). "Compared with the KLF15 KO mice, both contractile dysfunction (EF and FS) and cardiac hypertrophy (heart/body weight ratio, heart size, myocyte area and mRNA level of ANP, BNP) were improved in SB265610-treated KLF15 mice." (PMID 33869197, 2021). "Gene reporter studies show that KLF15 inhibits MEF2 and GATA4 DNA-binding transcriptional activation and that KLF15 negatively regulates cardiac hypertrophy by preventing DNA-binding of MEF2 and GATA4 to their transcriptional targets." (PMID 29702551, 2018). "The Kruppel like factor 15 (KLF15) is expressed in the heart and acts as a repressor of cardiac hypertrophy and fibrosis." (PMID 28400202, 2017). "Restoration of KLF15 prevents cardiac hypertrophy in response to pressure overload in wildtype mice but not in mutant mice deficient of BCAA degradation gene." (PMID 30050148, 2018). "Therefore, KLF15 acts as a negative repressor of cardiac hypertrophy via inhibitory competitive binding to myocardin." (PMID 29702551, 2018). "Our data show that the previously identified KLF15-dependent mechanisms regulating hypertrophy and fibrosis upon induced cardiac hypertrophy are not activated in absence of any stimuli, suggesting an alternative mechanism through which KLF15 controls normal cardiac homeostasis." (PMID 22767436, 2012).